CD72 (CD72 molecule)
Description:
Co-receptor of B cell receptor (BCR) that plays both positive and negative roles on B-cell functions. Recognizes the Sm/ribonucleoprotein (RNP) self-antigen ligand, and coligation of CD72 and BCR inhibits BCR signaling. Mechanistically, ligand binding leads to the recruitment of PTPN6/SHP-1 to the BCR complex which is inhibitory to BCR signaling. Also acts as a ligand for CD5 and thereby plays a critical role in maintaining regulatory T and B-cell homeostasis.
Synonyms: LYB2; CD72b
Tractability: Antibody: its Gene Ontology location is reachable by antibodies, with high confidence; UniProt predicts a signal peptide or a membrane-spanning region.
Gene: Protein-coding gene on chromosome 9 (35,609,982 to 35,646,810, reverse strand). Ensembl gene ENSG00000137101.
Subcellular location: Membrane
Subcellular location (Human Protein Atlas): Mitochondria; Nucleoplasm
Pathways (Reactome):
Developmental Biology: Other semaphorin interactions
Gene Ontology:
Molecular function: protein binding; receptor ligand activity; transmembrane signaling receptor activity; signaling receptor binding
Biological process: negative regulation of B cell receptor signaling pathway; cell adhesion; signal transduction
Cellular component: plasma membrane; membrane
Genetic constraint (gnomAD): Loss-of-function variants: 21 observed, 36.37 expected, observed/expected ratio (o/e) 0.58, 90% interval 0.41 to 0.83. The upper end of that interval is the gene's LOEUF score, 0.83, which puts it in group 3 of 6, group 1 being the genes least tolerant of losing a copy. Missense variants: 317 observed, 347.86 expected, observed/expected ratio (o/e) 0.91, 90% interval 0.83 to 1. Synonymous variants: 143 observed, 145.46 expected, observed/expected ratio (o/e) 0.98, 90% interval 0.86 to 1.13.
Homologues: Orthologues: chimpanzee CD72 (98% identical), macaque CD72 (86% identical), dog CD72 (62% identical), guinea pig CD72 (57% identical), pig CD72 (55% identical), mouse Cd72 (53% identical), rat Cd72 (51% identical).
Diseases named in the same sentence as CD72 in open-access papers:
CD72 is named in the same sentence as 57 diseases in open-access papers, as found by Europe PMC text mining. Sharing a sentence is not in itself a finding about the gene and the disease. The quoted sentences say what the papers report.
systemic lupus erythematosus (10 papers, 2012 to 2026). An autoimmune multi-organ disease typically associated with vasculopathy and autoantibody production. "For example, CD72 is strongly associated with developing systemic lupus erythematosus (SLE) in autoimmune diseases." (PMID 37980541, 2023). "We previously demonstrated significant association of the polymorphism of the CD72 gene with susceptibility to human systemic lupus erythematosus (SLE) in individuals carrying a SLE-susceptible FCGR2B genotype (FCGR2B-232Thr/Thr)." (PMID 23268649, 2012). "CD72 is a C-type lectin-like domain receptor expressed by B cells, pDCs, cDC2s, macrophages, and NK cells and binds the lupus self-antigen ribonucleic protein Sm." (PMID 39007135, 2024). "In contrast, soluble CD72 (sCD72) is reported to be increased in the serum of autoimmune diseases such as systemic lupus erythematosus and primary Sjogren’s syndrome (pSS)." (PMID 39026665, 2024). "In patients with Systemic Lupus Erythematosus, low expression of CD72 on B cells is negatively correlated with patient disease activity (SLEDAI)." (PMID 35957889, 2022). "Nonetheless, CD72−/− mice develop lupus-like disease that is clearly more severe than that developed in mice deficient in other inhibitory co-receptors." (PMID 30333834, 2018). "We demonstrated that the extracellular CTLD of CD72 specifically recognizes the lupus self-antigen Sm/RNP as a ligand." (PMID 30333834, 2018). "This ligand recognition recruits CD72 to BCR in Sm/RNP-reactive B cells thereby suppressing production of anti-Sm/RNP autoantibody involved in the pathogenesis of lupus." (PMID 30333834, 2018). "In contrast, the protein product of the alternative splicing isoform of CD72 (CD72Δex8), which is reportedly a susceptibility gene of systemic lupus erythematosus, is not degraded by the proteasome and accumulates in the endoplasmic reticulum." (PMID 36271469, 2022). "CD72 appears to inhibit development of lupus by inhibiting activation of Sm/RNP-reactive B cells." (PMID 30333834, 2018). "Almost all CD72−/− mice spontaneously develop lupus-like glomerulonephritis by 6 months of age." (PMID 30333834, 2018). "Upon BCR stimulation, lupus CD72-negative SWM and DN2 B cells displayed increased pSYK phosphorylation compared with their CD72-positive counterparts and the overall cell population." (PMID 41738264, 2026). "In CD72−/− mice, Sm/RNP activates B cells reactive to Sm/RNP probably by inducing both BCR signaling and TLR7 signaling, leading to the production of anti-Sm/RNP antibody crucial for development of lupus." (PMID 30333834, 2018). "The relative resistance of CD72-negative B cells to RTX indicates that an impaired checkpoint programme in lupus B cells may potentially contribute to disease relapse." (PMID 41738264, 2026).
leukemia (6 papers, 2007 to 2025). A malignant (clonal) hematologic disorder, involving hematopoietic stem cells and characterized by the presence of primitive or atypical myeloid or lymphoid cells in the bone marrow and the blood. "The interactions between CD100 and CD72 might be important in killing of transformed cells such as leukemia of B cell origin, which express CD72 on their surface." (PMID 17786190, 2007). "Similarly, we showed that PAX5, EBF1, CD72 and TCL1A are tightly correlated in the capacity to distinguish lymphoblastic and myeloblastic characteristics also in the presence of MLL mutations illustrating the importance of B-cell receptor signaling pathway in this subset of leukemias." (PMID 19549311, 2009). "Deregulation events of CSRP2, TCL1A, CD72 and EBF genes in acute pediatric leukaemia have been previously reported using gene expression profiling." (PMID 19549311, 2009). "Importantly, CD72 expression was maintained in CD19-negative cells and CD72 CAR-T cells effectively eliminated CD19-negative leukemia cells in vitro and in vivo." (PMID 35681499, 2022).
autoimmune disease (5 papers, 2017 to 2024). A disorder resulting from loss of function or tissue destruction of an organ or multiple organs, arising from humoral or cellular immune responses of the individual to their own tissue constituents. "This explains the synergy of genetic defects such as deficiency of Fas and Bim85–87 and deficiency of CD72 and Fas70 in the development of severe autoimmune disease." (PMID 28408984, 2017). "Soluble CD72 was found to be higher in the serum of patients with autoimmune diseases such as SLE and Sjogren’s syndrome as compared to healthy controls." (PMID 39026665, 2024). "Among them, TGFBR1, TGFBR2, CCL5, CD48, CD244A, and CD72 have been reported to be closely related to the pathophysiologic processes of autoimmune diseases." (PMID 35515003, 2022). "CD72 −/− mice develop lupus-like syndrome and CD72 is downregulated in humans diagnosed with lupus erythematosus, indicating the involvement of CD72 in the pathogenesis of autoimmune diseases." (PMID 35681499, 2022). "Thus, SHP-1 regulates B-1 cell expansion and development of lupus-like disease through distinct SHP-1-recruiting receptors, Siglec-G and CD72, respectively, and B-1 cell expansion does not necessarily associate with development of autoimmune disease." (PMID 28408984, 2017). "And CD72, being a co-receptor of B cell receptor (BCR), has been reported to be an important regulator in the pathogenesis of several autoimmune diseases." (PMID 32306893, 2020). "Several studies have reported the aberrant expression of CD72 on B cells in autoimmune diseases and suggested that it has both positive and negative effects on B cell development and function." (PMID 32306893, 2020).
Autoimmunity (5 papers, 2018 to 2026). The occurrence of an immune reaction against the organism's own cells or tissues. "Wenotably described for the first time in B cells the interaction between Trib1 and COP1,and with CD72, a negative regulator of B cells whose deficiency in mice leads to thedevelopment of autoimmunity." (PMID 29599769, 2018). "Interestingly, we find an interactionbetween Trib1 and CD72, a negative regulator of B cells whose deficiency in miceleads to the development of autoimmunity." (PMID 29599769, 2018). "Of note, TRIB1 is shown to negatively regulate B cells in systemic lupus erythematosus via its interaction with CD72, an effector of autoimmunity." (PMID 38791967, 2024). "Indeed, this appears to be the case for anti-Sm autoimmunity, which is restrained by CD72 under normal circumstances." (PMID 37833897, 2023).
lymphoma (5 papers, 2017 to 2025). A malignant (clonal) proliferation of B- lymphocytes or T- lymphocytes which involves the lymph nodes, bone marrow and/or extranodal sites. "A gene involved in formation of tight junctions showed inherent upregulation in resistant line 61 BMDMs (CLDN5), whereas CD72, which is involved in lymphoma of the small intestine, was highly expressed in MD-susceptible chickens." (PMID 30678299, 2019). "Of the 579 overrepresented proteins, six proteins were found in at least 20-fold higher abundance in lymphoma patients (NUCKS1, SLC14A1, GPALPP1, ADPRH, CD72, PRDM15)." (PMID 33562532, 2021). "Microarray analyses revealed significant upregulation of a multitude of NK-activating and costimulatory ligands across varied b-NHL cell lines and primary lymphoma cells, including ULBP1, CD72, CD48, and SLAMF6." (PMID 29312292, 2017).
B cell lymphomas (3 papers, 2017 to 2025). "Top proteins that were consistently associated with B-cell lymphoma across the EPIC, ARIC and UK Biobank cohorts included: CXCL13, sCD23, FCRL1, FCRL3, SEMA7A, CD72, CD48, LY9 and VCAM1." (PMID 40894013, 2025). "CD72 is also abundantly expressed in B cell-derived neoplasms, including B-ALL, CLL, and B cell lymphomas." (PMID 35681499, 2022).
multiple sclerosis (3 papers, 2020 to 2024). A progressive autoimmune disorder affecting the central nervous system resulting in demyelination. "In multiple sclerosis, the expression of CD72 decreased along with an increase in expression of its ligand CD100 on T cells and abnormal levels of several inflammatory factors." (PMID 32306893, 2020). "CD72 is lowly expressed in multiple sclerosis and its ligand CD100 is increased in T cells." (PMID 35957889, 2022). "Moreover, the expression of CD72 on B cells also decreased in patients with multiple sclerosis." (PMID 32306893, 2020). "In a variety of diseases (Kawasaki disease, multiple sclerosis, and rheumatoid arthritis), the SEMA4D/CD72 axis leads to increased levels of cytokines and results in worse prognosis." (PMID 39329961, 2024).
viral infection (3 papers, 2022 to 2024). "We next again assessed if immunization or viral infection influenced inhibitory receptor expression on DN2 B cells by measuring CD72 and CD22 surface expression." (PMID 36131937, 2022). "Because severe viral infection results in phenotypically activated unswitched and switched memory B cells, we sought to determine if activation of the memory B cell populations also coincides with a reduction in inhibitory receptors by memory B cells through evaluation of CD72 and CD22." (PMID 37638016, 2023). "Compared to cluster 4, cluster 2 cells showed higher expression of SLAMF7, ZEB2, GZMB, GPR18, CD72, PDCD1 (PD1) and CRTAM that are known to be expressed in terminally differentiated effector cells in viral infections and various cancers." (PMID 38501302, 2024). "The mean fluorescence intensity (MFI) of CD72 was found to be expressed at a higher level on DN2 cells from immunized individuals and those with mild viral infection compared to healthy controls." (PMID 36131937, 2022). "This suggests that DN2 cells naturally have the largest capacity to signal through the BCR compared to other DN subsets, a process which may be independent of traditional inhibitory receptors (CD22, CD72, FcRL5) and/or that the function of inhibitory receptors is impaired during viral infection." (PMID 36131937, 2022).
acute lymphoblastic leukemia (2 papers, 2023 to 2025). Leukemia with an acute onset, characterized by the presence of lymphoblasts in the bone marrow and the peripheral blood. "Several studies have shown that CD72 is a marker for progenitor cell B-cell leukemia and a new marker for detecting microscopic residual disease in acute lymphoblastic leukemia." (PMID 37980541, 2023). "Some studies have shown that CD72 influences the development and progression of colorectal cancer, nasopharyngeal cancer, and acute lymphoid leukemia." (PMID 37980541, 2023).
acute myelogenous leukemia (2 papers, 2018 to 2019). "In an acute myeloid leukemia cell line Kasumi-1, Sema4D binding of CD72, its preferred receptor in immune cells, leads to inhibition of growth and cell death, as a result of phosphorylation of CD72, the formation of the CD72–SHP-1 complex and dephosphorylation of src family kinases and JNK." (PMID 29971044, 2018). "Another study assessed the growth-suppressing activity of CD72, the low affinity receptor of SEMA4D, in acute myelogenous leukemia (AML) cells." (PMID 31143707, 2019).
HIV-1 infection (2 papers, 2018 to 2023). The type species of lentivirus and the etiologic agent of acquired immunodeficiency syndrome (AIDS). "In addition to HIV-1-specific T-cell dysfunction, it was also observed that PD-1/PD-L1 and CD72/CD100 markers on B cells were significantly enhanced during active HIV-1 infection." (PMID 38193090, 2023). "In HIV-1 infection, immune cell dysregulation is multifactorial, and recent publications indicate that CD72/CD100 may play a relevant role in immune regulation." (PMID 30161254, 2018). "In addition, PD-1/PD-L1 may be involved with CD72/CD100 in the formation of immune disorders during human immunodeficiency virus (HIV)-1 infection." (PMID 38193090, 2023). "Our data suggest that the CD72/CD100 and PD-1/PD-L1 axes may jointly participate in dysregulation of immunity during HIV-1 infection and could partially explain the immune systems’ hyper-activation and exhaustion." (PMID 30161254, 2018). "Immune system dysfunction during HIV-1 infection is undoubtedly multifactorial, but accumulating evidence indicates that CD100 and CD72 may play an important role in immune dysregulation of effector cell functions." (PMID 30161254, 2018). "Interestingly, little is known about the relationships between CD72/CD100 and PD-1/PD-L1 axes in the context of HIV-1 infection." (PMID 30161254, 2018). "However, it is still unclear what role the CD72/CD100 axis has during normal immune responses and HIV-1 infections." (PMID 30161254, 2018).
Lung fibrosis (2 papers, 2021 to 2022). "Thus, deficiency of CD22 or CD72 or both decreased bleomycin-induced lung fibrosis." (PMID 35860745, 2022). "Lung fibrosis scores were significantly better in mutant mice (CD22-deficient, CD72-deficient and CD22 and CD72 double-deficient mice) compared to wild type mice (mice without CD22 or CD72 deficiency)." (PMID 35860745, 2022). "Loss of inhibitory molecules, either CD22 or CD72, decreased skin and lung fibrosis revealing a role for both negative co-receptors of BCR signaling in disease pathogenesis." (PMID 35860745, 2022). "CD22−/−, CD72−/− and CD22−/−CD72−/− mice transfused with B cells from wild-type mice demonstrated skin and lung fibrosis comparable to that encountered in wild type mice." (PMID 35860745, 2022). "A recent study by Zhao demonstrated the contribution of CD22 and CD72 in a murine scleroderma model reporting a marked reduction in skin and lung fibrosis severity in CD22−/−, CD72−/−, and CD22−/−/CD72−/− mice in comparison to wild-type (WT) mice in the bleomycin-induced model." (PMID 34071314, 2021).
lupus nephritis (2 papers, 2018 to 2020). Glomerulonephritis in the context of systemic lupus erythematosus. "In SLE patients, the lower expression of CD72 on B cells was inversely associated with patients’ disease activity (SLEDAI) and correlated with the presence of lupus nephritis, anti-dsDNA antibodies and low levels of complement." (PMID 32306893, 2020).
melanoma (2 papers, 2015 to 2025). A malignant, usually aggressive tumor composed of atypical, neoplastic melanocytes. "Our integrative genetic analyses revealed that higher CD72 levels are causally associated with reduced melanoma risk, suggesting a protective role, potentially through immunoregulatory pathways." (PMID 41148223, 2025). "Taken together, our findings highlight CD72 as a novel immune-protective target in melanoma and identify Dihydroergotamine as a promising pharmacological agent for further evaluation." (PMID 41148223, 2025). "Among them, Dihydroergotamine emerged as the top-ranked candidate, exhibiting the strongest predicted binding affinity to CD72 (−10.16 kcal/mol), which highlight the potential for drug repurposing strategies targeting CD72 in melanoma treatment." (PMID 41148223, 2025). "In contrast to other proteins such as CCL11 and LYZ, whose roles in melanoma are relatively well-established, CD72 represents a less-characterized but promising target." (PMID 41148223, 2025). "For instance, our microarray data revealed significant downregulation of Cd72 (9.93-fold, p < 0.001) and Fas (9.91-fold, p < 0.01) gene expression in B16-F1 melanoma." (PMID 26441959, 2015). "Future work will focus on molecular dynamics simulations, ligand binding validation, and functional assays to determine whether Dihydroergotamine can act as a CD72 agonist and suppress melanoma progression through immune modulation." (PMID 41148223, 2025). "Among these, CD72 and LYZ emerged as promising therapeutic targets, supported by prognostic and predictive value in multiple melanoma cohorts." (PMID 41148223, 2025). "CD72 functions as a cell adhesion and costimulatory ligand for the CD5 receptor on T cells, and its downregulation may limit high-affinity interactions between melanoma cells and tumor antigen-specific T cells." (PMID 26441959, 2015).
nasopharyngeal carcinoma (2 papers, 2022 to 2023). A carcinoma arising from the nasopharyngeal epithelium. "CD72 may be an independent predictor of prognosis in nasopharyngeal carcinoma patients." (PMID 37980541, 2023). "We examined the expression of BTK, CD72, PTPN6, and VAV1 in NPC cell lines by qRT-PCR, and the expression levels of BTK, CD72, PTPN6, and VAV11 were lower in human nasopharyngeal carcinoma SUNE-1 cells compared with human nasopharyngeal epithelial cells NP69 (P<0.05)." (PMID 35957889, 2022).
primary Sjogren’s syndrome (2 papers, 2020 to 2024). "Another study on primary Sjogren’s syndrome (pSS) reported that the soluble CD72 serum levels in patients were higher than those found in the healthy controls." (PMID 39026665, 2024).
scrapie (2 papers, 2011 to 2020). A fatal disease of the nervous system in sheep and goats, characterized by pruritus, debility, and locomotor incoordination. "Transfusion of CD72+ B lymphocytes or CD21+ B lymphocytes from scrapie infected sheep resulted in PrPSc detection in lymphoid tissues of recipients." (PMID 22112371, 2011). "Prion infectivity was detected in circulating PBMCs, CD72+ pan B lymphocytes, the CD21+ subpopulation of B lymphocytes and platelet-rich plasma of classical scrapie infected sheep using a sheep bioassay." (PMID 22112371, 2011).
aneurysm (1 paper, 2009). Bulging or ballooning in an area of an artery secondary to arterial wall weakening. "Genes that can be considered as markers for the following cell types were upregulated in aneurysms: neutrophils (Csf3r); T lymphocytes (Cd3d) and B lymphocytes (Blnk, Cd72, various immunoglobulin genes); and monocyte/macrophages (Cd14, Cd68)." (PMID 19580648, 2009).